MBOAT7 (membrane bound acylglycerophosphatidylinositol O-acyltransferase MBOAT7)
Diseases named in the same sentence as MBOAT7 in open-access papers (continued):
Sharing a sentence is not in itself a finding about the gene and the disease.
hepatocellular carcinoma (15 papers, 2017 to 2026). A malignant tumor that arises from hepatocytes. "On the other hand, data from the GEPIA portal show that higher MBOAT7 expression in hepatocellular carcinoma tumors is associated with worse prognosis." (PMID 38893234, 2024). "We observed in hepatoma cells that the silencing of the MBOAT7 and TM6SF2 genes led to an enhanced release of ccf-mtDNA, whose levels were conversely reduced in overexpressed cells." (PMID 40563253, 2025). "Increased MBOAT7 expression correlates with detrimental outcomes in some cancers, including hepatocellular carcinoma and renal clear cell carcinomas, suggesting a dependency on the enzyme." (PMID 37316513, 2023). "The risk of developing a hepatocellular carcinoma from NAFLD can be assessed using the Polygenic Risk Score-5, which combines PNPLA3, TM6SF2, GCKR, and MBOAT7." (PMID 37999211, 2023). "This work also showed that genetic deletion of MBOAT7 in human hepatoma cell lines can promote triacylglycerol accumulation in a cell autonomous manner by both limited fatty acid oxidation and promoting de novo lipogenesis." (PMID 35636492, 2022). "Conversely, increased MBOAT7 expression is correlated with detrimental outcomes in cancers, such as hepatocellular carcinoma and clear cell renal carcinomas, suggesting that inhibitors of MBOAT7 may be useful therapeutic agents." (PMID 37316513, 2023). "Moreover, the rs641738 C>T variant in the MBOAT7 gene as well as the loss-of-function rs1260326 C>T variant in the GCKR gene are related to inflammation, increased susceptibility to NASH, fibrosis, and hepatocellular carcinoma (HCC)." (PMID 35739957, 2022). "Furthermore, we show that genetic deletion of MBOAT7 in Huh7 hepatoma cells can promote cell autonomous increases in cytosolic lipid droplets, and this enhanced lipid storage is associated with augmented lipogenesis rates and reduced fatty acid oxidation rates." (PMID 31621579, 2019). "Specifically, the rs641738 variant of the MBOAT7 gene, which promotes the regulation of insulinemia, has been evaluated as a predisposing factor of hepatocellular carcinoma (HCC), even in the absence of cirrhosis in MAFLD patients." (PMID 36984595, 2023). "Another interesting finding in this work was that in hepatoma cells lacking MBOAT7, there was an apparent overexpression of key lipid transporter called fatty acid transport protein 1 (FATP1)." (PMID 35636492, 2022).
Insulin resistance (13 papers, 2019 to 2026). Increased resistance towards insulin, that is, diminished effectiveness of insulin in reducing blood glucose levels. "Our data demonstrate that MBOAT7 is a critical regulator of adipose tissue PI homeostasis, and adipocyte MBOAT7-driven PI biosynthesis is closely linked to hyperinsulinemia and insulin resistance in mice." (PMID 36806709, 2023). "Together, these data indicate that LPI-18:1 can alter the gonadal adipose tissue phosphoproteome in a MBOAT7-dependent manner and this is associated with pathways linked to insulin resistance." (PMID 36806709, 2023). "This work further showed that Mboat7 loss of function promotes striking hyperinsulinemia and hepatic insulin resistance in high-fat diet-fed mice." (PMID 35636492, 2022). "Thus, the insulin resistance phenotype appears to be largely selective to loss of MBOAT7 in adipocytes." (PMID 37127068, 2023). "Given the fact that obesity is commonly associated with insulin resistance and type 2 diabetes mellitus, we also examined the relationship between Mboat7 expression and insulin sensitivity in the HMDP." (PMID 31621579, 2019). "Collectively, these data suggest that MBOAT7 may be mechanistically linked to the well-known association between obesity, insulin resistance, and NAFLD progression." (PMID 31621579, 2019). "Here, we show that MBOAT7 function in adipocytes contributes to diet-induced metabolic disturbances including hyperinsulinemia and systemic insulin resistance." (PMID 36806709, 2023). "Collectively, these data support a clear cell autonomous role for MBOAT7-driven acylation of LPI lipids as a key protective mechanism against obesity-linked NAFLD progression, hyperinsulinemia, and systemic insulin resistance." (PMID 36806709, 2023). "Another key question that has come from mouse studies is how to reconcile the fact that either ASO- or MPO-mediated silencing of Mboat7 (which can target multiple cell types) promotes profound hyperinsulinemia and systemic insulin resistance." (PMID 35636492, 2022). "Mouse Studies of Mboat7 Loss of Function To explore the role of Mboat7 in diet-induced obesity, NAFLD progression, and insulin resistance, we utilized an in vivo knockdown approach in 8-week old adult mice." (PMID 31621579, 2019). "Using KEGG pathway analysis, we find that indeed LPI-18:1 significantly induces a phosphopeptide signature associated with insulin signaling and insulin resistance in mice lacking MBOAT7 function in adipocytes (Mboat7ASKO mice)." (PMID 36806709, 2023). "Moreover, we found that adipocyte-specific genetic deletion of Mboat7 is sufficient to promote hyperinsulinemia, systemic insulin resistance, and mild fatty liver." (PMID 36806709, 2023). "One possibility, therefore, was that suppression of MBOAT7 expression in adipose tissue could explain the insulin resistance observed by Helsley and colleagues." (PMID 37127068, 2023). "It is reasonable to assume that the abundant expression of Mboat7 in adipose tissue or myeloid cells may play a role in systemic insulin resistance, but additional studies are required to formally test this hypothesis." (PMID 35636492, 2022). "Interestingly, MBOAT7 is downregulated by acute injection of insulin in both liver and adipose tissue, suggesting the possibility that hyperinsulinemia might worsen systemic insulin resistance through downregulation of MBOAT7." (PMID 37127068, 2023). "This manuscript builds on our initial observation that ASO-mediated knockdown of Mboat7 promotes NAFLD progression, hyperinsulinemia, and insulin resistance in mice." (PMID 38648183, 2024). "This article builds on our initial observation that ASO-mediated knockdown of Mboat7 promotes NAFLD progression, hyperinsulinemia, and insulin resistance in mice." (PMID 36806709, 2023). "Emerging evidence supports genetic determinants of FLD (eg PNPLA3, TM6SF2, MBOAT7, GCKR, HSD17B13) as determinants of insulin resistance and T2D." (PMID 33102799, 2020).
Insulin resistance (continued). "The authors further showed that MBOAT7 is decreased in humans and rodents with obesity and highlighted a strong negative correlation between hepatic MBOAT7 expression with insulin resistance and obesity." (PMID 41032702, 2025). "Furthermore, we demonstrated that ASO-mediated knockdown of Mboat7 in HFD fed mice elicits profound hyperinsulinemia and systemic insulin resistance." (PMID 36806709, 2023). "Analysis of liver pathology and insulin resistance in these mice revealed that liver-targeted deletion of MBOAT7 resulted in a fatty liver phenotype but not insulin resistance, consistent with previous studies." (PMID 37127068, 2023). "However, we found that the deletion of MBOAT7 in liver does not lead to insulin resistance or altered insulin signaling in liver, as there was no change in the basal plasma glucose concentration." (PMID 32859645, 2021). "However, when MBOAT7 deletion was subsequently introduced specifically in hepatocytes, the fatty liver phenotype observed in the MBOAT7 antisense oligonucleotide studies above was replicated, but not the insulin resistance." (PMID 37127068, 2023).
Hyperinsulinemia (11 papers, 2019 to 2025). An increased concentration of insulin in the blood. "In the presence of the T allele, as well as in the case of hyperinsulinemia, MBOAT7 expression (and function) results as impaired, promoting the formation of saturated phospholipids." (PMID 34063372, 2021). "This latter, in the presence of MBOAT7 rs641738 C>T variant, is most favoured by hyperinsulinemia, as well as the assumption of saturated FAs." (PMID 34063372, 2021). "Specifically, in presence of severe obesity and hyperinsulinemia, MBOAT7 is downmodulated both in patients and in rodents, independently of the genetic background." (PMID 34680476, 2021). "Mboat7 ASO-treated mice also exhibited profound hyperinsulinemia in the fasted state and throughout an intraperitoneal glucose tolerance test." (PMID 31621579, 2019). "Another particularly striking finding from the current study is that Mboat7 knockdown promotes severe hyperinsulinemia." (PMID 31621579, 2019). "Conversely, although fasting plasma insulin levels were elevated in fat-fed mice lacking MBOAT7 in hepatocytes, deletion of MBOAT7 in adipocytes caused hyperinsulinemia and reduced insulin sensitivity, with only minor effects on the liver fat." (PMID 37127068, 2023). "In this arena, MBOAT7 suppression, a MAFLD progression-associated mechanism, could also be particularly implicated due to the downregulating effect of hyperinsulinemia over the gene expression, providing NAFLD progression and further cardiovascular damage." (PMID 36079118, 2022). "The MBOAT7 variant (rs641738 C>T MBOAT7/TMC4) reduces the levels of the MBOAT7 protein in the liver and predisposes to advance forms of NAFLD, mainly by modifying the hepatic levels of phosphatidylinositol (PI) and LPI and stimulating hyperinsulinemia and hepatic IR." (PMID 37106795, 2023). "The inconsistencies in the human association studies may be explained in part by the ability of obesity and/or hyperinsulinemia to suppress MBOAT7 mRNA and protein levels, which appears to be independent of and in addition to the rs641738-mediated suppression of MBOAT7 expression." (PMID 35636492, 2022).
Intellectual disability (10 papers, 2019 to 2023). "MBOAT7 deficiency in humans leads to developmental disorders of the central nervous system, with intellectual disability, epilepsy and autism spectrum disorder." (PMID 37316513, 2023). "In this study, we identified a novel MBOAT7 variant in siblings that shared clinical phenotype, intellectual disability, seizure, and common brain MRI findings." (PMID 35509994, 2022). "Several follow-up studies have identified >16 loss-of-function mutations in the human MBOAT7 gene, most of which are associated with intellectual disability, developmental delay, epilepsy, microencephaly or macroencephaly, and autism-like phenotypes." (PMID 35636492, 2022). "A prominent finding of this study is that molecular modeling of human MBOAT7 predicted the molecular pathomechanisms of the MBOAT7 variant in patients with intellectual disabilities." (PMID 35509994, 2022). "The membrane-bound O-acyltransferase domain-containing 7 (MBOAT7) gene is associated with intellectual disability, early onset seizures, and autism spectrum disorders." (PMID 35509994, 2022). "MBOAT7 was recently reported to be associated with intellectual disabilities and autism spectrum disorders." (PMID 35509994, 2022). "Variants in the membrane-bound O-acyltransferase family member 7 (MBOAT7) which encodes LPIAT1 is involved in intellectual disability associated with epilepsy and autism spectrum disorder (ASD)." (PMID 34831185, 2021). "Heterogeneous clinical features were associated with MBOAT7 defect, such as moderate to severe intellectual disability, epilepsy, developmental delay, attention-deficit hyperactivity disorder (ADHD), microcephaly or macrocephaly, and autistic features." (PMID 33335874, 2020). "MBOAT7 gene variants have recently been identified as a cause of intellectual disability (ID), seizures and autistic features." (PMID 31852446, 2019). "In addition to the common polymorphism near the MBOAT7 gene, several homozygous null mutations (Online Mendelian Inheritance in Man: 606048) have been identified in subjects with severe intellectual disability, epilepsy, and autistic phenotypes." (PMID 35636492, 2022). "In conclusion, the study adds to the phenotypic and genetic spectrum of MBOAT7- and TRAPPC9-related intellectual disability." (PMID 36672789, 2022). "The lack of LPLAT11 (MBOAT7) in mice, which is specific for lysoPI, and prefers 20:4 as FA substrate, leads to disordered cortical lamination and delayed neuron migration, and novel loss of function mutations were associated with intellectual disability." (PMID 35225335, 2022).
nonalcoholic fatty liver disease (10 papers, 2018 to 2025). "Recently, researchers discovered that the rs641738 membrane-bound O-acyltransferase domain-containing 7 (MBOAT7) polymorphism influences histological liver damage in alcoholic liver disease, nonalcoholic fatty liver disease, and chronic hepatitis B (CHB)." (PMID 36290765, 2022). "Previous large-scale genetic studies identified single nucleotide polymorphisms (SNPs) of the TM6SF2 and MBOAT7 genes as risk factors for alcoholic liver cirrhosis and non-alcoholic fatty liver disease." (PMID 30875804, 2019). "Consistent with the genome-wide association study, silencing MBOAT7 by an antisense oligonucleotide, which resulted in lower MBOAT7 expression primarily in liver, adipose tissue, and cells within the reticuloendothelial system, caused a nonalcoholic fatty liver disease phenotype in fat-fed mice." (PMID 37127068, 2023). "Non-alcoholic fatty liver disease (NAFLD) is thought to emerge from a state of insulin resistance (IR) as the product of an interaction between the obesogenic environment and genetically predisposing alleles (e.g., I148M in PNPLA3, E167K in TM6SF2, MBOAT7 rs641738 variant)." (PMID 31426291, 2019).
fibrosis (9 papers, 2016 to 2025). the formation of excess fibrous connective tissue in an organ or tissue in a reparative or reactive process. "Recently, the rs641738 genotype, encoding the membrane bound O-acyltransferase domain-containing 7 (MBOAT7), was associated with more severe liver damage and increased risk of fibrosis in NASH patients; however, these findings need further investigation regarding HCC progression." (PMID 30228976, 2018). "Finally, rs641738 C>T near MBOAT7 was found to have a strong association with phosphatidylinositols (PI), which was not replicated in any other NASH-fibrosis SNP (for example, PI C18:0/C20:4: β −0.2, Q = 1.7 × 10–58)." (PMID 32720691, 2020). "This hypothesis is supported by the observed negative correlation between hepatic MBOAT7 expression and the extent of liver inflammation and the elevated hepatic MBOAT7 expression in CHC patients with no or mild fibrosis, compared with controls." (PMID 27630043, 2016).
Obesity (8 papers, 2019 to 2025). Accumulation of substantial excess body fat. "To follow up on our findings in human obesity, we also examined hepatic expression levels of Mboat7 in obese leptin-deficient mice and high fat diet-fed rats." (PMID 31621579, 2019). "Collectively, these data support a role for Mboat7-driven acylation of LPI lipids as a key protective mechanism against obesity-linked NAFLD progression." (PMID 31621579, 2019). "In agreement, we found that high fat diet-induced obesity in Sprague-Dawley rats was also associated with significant reductions in hepatic Mboat7 expression." (PMID 31621579, 2019). "Reduced MBOAT7 expression in adipose tissue may cause insulin resistance in obesity, as shown by experiments in mice with adipose tissue knockout of this gene." (PMID 38893234, 2024). "To test whether MBOAT7 impacts obesity-linked NAFLD progression we utilized an in vivo knockdown approach in high fat diet-fed C57BL/6 mice." (PMID 31621579, 2019). "The expression of Mboat7 in white adipose tissue closely correlates with diet-induced obesity across a panel of ∼100 inbred strains of mice fed a high fat/high sucrose diet." (PMID 36806709, 2023). "We next postulated that under conditions such as obesity where Mboat7 activity is diminished, LPI-driven signaling can be sustained and promote liver injury." (PMID 31621579, 2019).
liver cirrhosis (5 papers, 2018 to 2025). "In the ALD cohort, association of liver cirrhosis remained significant also after further adjusting for risk variants of other well-established ALD genetic modifiers (PNPLA3, TM6SF2 and MBOAT7)." (PMID 34638908, 2021). "PNPLA3 has not only been associated with the development of liver cirrhosis and HCC, but has also shown a stronger association when compared with other risk alleles (e.g., SERPINA1, TM6SF2, MBOAT7 or GCKR)." (PMID 33804385, 2021). "PI 38:4 is a main product of MBOAT7; however, it is unclear whether the activity of this enzyme is reduced in liver cirrhosis." (PMID 41301814, 2025).
alcoholic cirrhosis (4 papers, 2016 to 2024). "More recently, transmembrane 6 superfamily member 2 (TM6SF2) and membrane-bound O-acyltransferase domain-containing protein 7 (MBOAT7) gene polymorphisms have been identified as risk factors for alcoholic liver cirrhosis." (PMID 30875804, 2019). "A recent GWAS identified rs641738, a polymorphism in the MBOAT7 locus, as being associated with the development of alcoholic cirrhosis." (PMID 27630043, 2016). "A GWAS found that the rs641738 variant, located in the 30 untranslated region of the gene encoding membrane-bound O-acyltransferase-domain-containing 7 (MBOAT7), specifically lysophosphatidylinositol-acyltransferase 1, is associated with an elevated risk of alcoholic cirrhosis." (PMID 39126031, 2024). "Variants of transmembrane 6 superfamily member 2 (TM6SF2) and membrane-bound O-acyltransferase domain-containing protein 7 (MBOAT7) gene polymorphisms are identified as risk factors for alcoholic liver cirrhosis (p = 7.89 × 10−10 and p = 1.03 × 10−9, respectively)." (PMID 36077080, 2022).
alcoholic liver diseases (4 papers, 2017 to 2025). A disorder caused by damage to the liver parenchyma due to alcohol consumption. "While our genetic assays were not specifically designed to differentiate between metabolic and alcohol-related liver disease, emerging evidence suggests that certain variants—particularly PNPLA3 rs738409 and MBOAT7 rs641738—are enriched in both MASLD and alcoholic liver disease." (PMID 40650184, 2025).
epilepsy (4 papers, 2021 to 2022). A brain disorder characterized by episodes of abnormally increased neuronal discharge resulting in transient episodes of sensory or motor neurological dysfunction, or psychic dysfunction. "MBOAT7 gene mutation or abnormal expression has been associated with mental impairment, epilepsy, and changes in MRI signals of the cerebral pallidus." (PMID 36704228, 2022).
viral hepatitis (4 papers, 2016 to 2026). An acute or chronic inflammation of the liver parenchyma caused by viruses. "We demonstrated strong MBOAT7 expression on all immune cell subsets that infiltrate the liver during viral hepatitis." (PMID 27630043, 2016). "Well-characterized variants such as PNPLA3, TM6SF2, HSD17B13, and MBOAT7, along with less commonly studied loci and chromosomal alterations, are discussed in relation to major etiologies, including MASLD/MASH, viral hepatitis, alcohol-related liver disease, and autoimmune conditions." (PMID 41590522, 2026).
gastric cancer (3 papers, 2018 to 2022). A primary or metastatic malignant neoplasm involving the stomach. "For example, a gastric cancer risk allele carrier was observed to have downregulated expressions of MBOAT7." (PMID 32802843, 2020).